UBE2T (ubiquitin conjugating enzyme E2 T)
Diseases named in the same sentence as UBE2T in open-access papers (continued):
Sharing a sentence is not in itself a finding about the gene and the disease.
breast carcinoma (continued). "Furthermore, Pearson’s correlation analysis showed that UBE2T expression was negatively related to miR-543 expression in breast cancer tissues." (PMID 34787051, 2021). "Additionally, UBE2T exhibited the opposite level to miR-543 in breast cancer and healthy tissues, indicating that UBE2T expression in breast cancer tissues was 2-fold higher than that of normal tissues." (PMID 34787051, 2021). "It has been demonstrated that UBE2T has a crucial role in the regulation of BRCA1 in breast cancer." (PMID 33313822, 2021). "Furthermore, another study suggested that UBE2T had a role in the pathophysiology of breast and lung tumors and affirmed the function of UBE2T in future clinical treatments for patients with breast cancer." (PMID 34787051, 2021). "Furthermore, miR-543 overexpression undermined the UBE2T promotional effect by inhibiting ERK/MAPK pathway activity in breast cancer cells." (PMID 34787051, 2021). "In breast cancer, UBE2T was shown to facilitate the polyubiquitination and degradation of BRCA1—an E3 ubiquitin ligase and a critical tumor suppressor gene in hereditary breast cancer--by interacting with the BRCA1/BRCA1-associated RING domain protein (BARD1) complex." (PMID 34257599, 2021). "Furthermore, we confirmed that the promotion effects of UBE2T on breast cancer malignancy by inhibiting ERK/MAPK activity." (PMID 34787051, 2021). "Furthermore, miR-543 inhibited breast cancer cell viability and cell proliferation via repressing UBE2T expression." (PMID 34787051, 2021). "Additionally, it was shown that UBE2T played a critical role in the development and/or progression of breast cancer through the interaction with and the regulation of the BRCA1/BARD1 complex." (PMID 34787051, 2021). "UBE2T expression is elevated in human prostate cancer, breast cancer, and lung cancer." (PMID 28427240, 2017). "In addition, UBE2T is overexpressed in breast cancer and silencing of UBE2T upregulates BRCA1 protein." (PMID 29156836, 2017). "In breast cancer it has been described that UBE2T has a critical role in the regulation of BRCA115." (PMID 29235520, 2017). "To ultimately define the role of UBE2T germline mutations in patients with breast/ovarian cancer, we performed whole exome sequencing using the Ilumina HiSeq platform on 450 BRCA1/2 WT high-risk breast cancer patients." (PMID 26085575, 2015). "In breast cancer, lung adenocarcinoma, liver hepatocellular carcinoma, skin cutaneous melanoma, prostate adenocarcinoma and adrenocortical carcinoma, the survival time of the group with high expression of UBE2T was shorter than that of the group with low expression." (PMID 39367897, 2025). "The interaction between UBE2T and Th1/Th2 may interfere with a positive breast cancer prognosis." (PMID 35578283, 2022). "However, we would also like to note that it is also possible that IFI6 may also influence cell growth and other tumor phenotypes by regulating alternative UBE2T-independent pathways to promote breast cancer cell growth." (PMID 36338541, 2022). "Therefore, our studies indicate that UBE2T acts as a facilitator of breast cancer growth and may represent a novel target for breast cancer therapy." (PMID 36338541, 2022). "In addition, UBE2T is overexpressed in breast cancer tissues." (PMID 35578283, 2022). "Therefore, we examined whether the inhibition of UBE2T expression prevents tumor growth in the highly prevalent luminal A breast cancer subtype." (PMID 36338541, 2022). "Additionally, the miR-543/UBE2T axis also participated in regulating breast cancer cell migration and invasion, which could be suppressed by miR-543 but promoted by UBE2T." (PMID 34787051, 2021). "Our study revealed that miR-543 impaired breast cancer progression by targeting UBE2T and downregulating UBE2T expression through the ERK/MAPK pathway, which suggested that miR-543 and UBE2T might serve as promising therapeutic gene targets for breast cancer in clinical application." (PMID 34787051, 2021).
breast carcinoma (continued). "This verified that miR-543 could target UBE2T in breast cancer cells." (PMID 34787051, 2021). "Moreover, further studies on its expression in breast cancer suggested that UBE2T could regulate cell proliferation and promote occurrence of tumor, suggesting its great potential as a new target for tumor therapy." (PMID 31969492, 2020). "UBE2T expression is regulated by transcription factor AP-2 alpha (TFAP2A), and UBE2T inhibition suppresses breast cancer tumor growth." (PMID 36338541, 2022). "Consistently, UBE2T inhibition downregulated IFI6 expression, promoting DNA replication stress, cell cycle arrest, and apoptosis and suppressing breast cancer cell growth." (PMID 36338541, 2022). "Cross-species genome comparison suggested that the genomic changes of UBE2T and UBE2C are related to the occurrence, development, and invasion of breast cancer." (PMID 35578283, 2022). "Nineteen genes from these gene sets were identified to be amplified and upregulated in breast cancer but only five of them NBN, PRKDC, RFWD2, UBE2T, and YWHAZ meet criteria in all breast cancer molecular subtypes." (PMID 33925616, 2021). "This research depicted that miR-543 targeted and repressed the expression of UBE2T to inhibit the ERK/MAPK pathway, which eventually inhibited the malignant behavior of breast cancer cells." (PMID 34787051, 2021). "Therefore, miR-543 and UBE2T could be promising prognostic targets for breast cancer." (PMID 34787051, 2021). "UBE2T, UBE2C, and BIRC5 amplifications predicted a worse survival and poor response to therapy across different intrinsic subtypes of breast cancer." (PMID 33671201, 2021). "Our results suggested that the miR-543/UBE2T axis and ERK/MAPK pathway be crucial in breast cancer diagnosis and provide new breast cancer treatment insights." (PMID 34787051, 2021). "The FA genes we identified as DEGs; CENPX, FAAP24, FANCD2, FANCI, UBE2T and FANCA are all overexpressed in breast cancer." (PMID 33662042, 2021). "We identified the ubiquitin-conjugating enzyme E2T (UBE2T) and the denticleless protein homolog (DTL) as upregulated in basal-like breast tumors and amplified in breast cancer." (PMID 29235520, 2017). "In contrast, down-regulation of UBE2T by RNAi stabilized BRCA1 and blocked cell growth in breast cancer cells." (PMID 27729585, 2016). "Similarly, in lung adenocarcinoma (LUAD), breast cancer (BCa), renal cell carcinoma (RCC), and osteosarcoma, the downregulation of UBE2T has been found to inhibit PI3K/AKT signaling activity and suppress cancer progression." (PMID 39791716, 2024). "Specifically, UBE2T overexpression resulted in the upregulation of the mTORC1 and TNFA signaling pathways, which facilitated cell cycle progression and inhibited apoptosis, thereby promoting breast cancer cell growth." (PMID 39791716, 2024). "Breast cancer cells with IFI6 inhibition displayed similar phenotypes as those with UBE2T inhibition, and ectopic IFI6 expression in UBE2T-knockdown breast cancer cells prevented DNA replication stress and apoptosis and partly restored breast cancer cell growth." (PMID 36338541, 2022). "In addition, ANLN and UBE2T were highly expressed in breast cancer, especially in TNBC and HER2-positive breast cancers compared with luminal A and luminal B breast cancers." (PMID 35578283, 2022). "To explore whether IFI6 plays a role in breast cancer cell growth downstream of UBE2T, we first examined whether IFI6 is overexpressed in patient-derived breast cancer samples compared with normal breast tissues, similar to UBE2T overexpression." (PMID 36338541, 2022). "Breast cancer gene expression datasets were downloaded from the GEO database, and original data were analyzed in R. The TIMER database was used to analyze the relationship between ANLN and UBE2T and immune cell infiltration." (PMID 35578283, 2022). "UBE2T overexpression may downregulate BRCA1 expression, promoting breast cancer development." (PMID 39367897, 2025).
breast carcinoma (continued). "Although, in our study we find that UBE2T mediates its function through IFI6 in UBE2T-IFI6-DNA replication-apoptosis pathway dependent manner in breast cancer cells, it is possible that IFI6 could influence cell growth and other phenotypes by alternative UBE2T-independent mechanisms." (PMID 36338541, 2022). "However, the knockdown of the other three transcription factors (ELK1, GTF2I and FOXP3) did not reduce UBE2T expression levels in breast cancer cells." (PMID 36338541, 2022). "In this study, we showed that the inhibition of UBE2T expression correlated with the repression of IFI6 expression, the activation of the DNA replication stress pathway, G1 cell cycle arrest, and apoptosis induction, leading to the inhibition of breast cancer cell growth and proliferation." (PMID 36338541, 2022). "However, the mechanism of UBE2T and miR-543 in regulating breast cancer development and progression has not been explored." (PMID 34787051, 2021). "Furthermore, miR-543 directly targeted UBE2T, and a negative correlation between miR-543 and UBE2T was also observed in breast cancer tissues." (PMID 34787051, 2021). "UBE2T has been also found overexpressed in lung, bladder and prostate cancers and may act as oncogene-like gene in breast cancer by repressing BRCA1 expression and promoting the proliferation and transformation of breast cancer cells." (PMID 26308072, 2015).
gastric cancer (25 papers, 2016 to 2025). A primary or metastatic malignant neoplasm involving the stomach. "However, few studies have examined UBE2T expression in gastric cancer, which is the number one cause of cancer-related death in China and a top cause of cancer-related death globally." (PMID 28427240, 2017). "UBE2T is involved in the Fanconi anemia (FA) DNA repair pathway and is often overexpressed in cancers such as breast and gastric cancers." (PMID 39851497, 2025). "Genetic inhibition of UBE2T in bladder and gastric cancer cells blocks cell proliferation and colony growth formation, underscoring the importance of this E2 in cancer cell growth and proliferation." (PMID 39851497, 2025). "Gastric cancer is one of the most prevalent cancers worldwide, with UBE2T reported to be significantly upregulated in gastric cancer tissues." (PMID 39791716, 2024). "More importantly, a recent study emphasized that CHPF is able to regulate the expression of E2F1 through UBE2T‐mediated ubiquitination, thus promoting gastric cancer development." (PMID 38775031, 2024). "UBE2T is crucial in promoting gastric cancer progression by mediating the ubiquitination and degradation of RACK1, which leads to the over-activation of the Wnt/β-catenin signaling pathway—a key driver of tumor progression." (PMID 39791716, 2024). "Collectively, the available evidence supports UBE2T as a promising biomarker and therapeutic target in gastric cancer." (PMID 39791716, 2024). "This relationship suggests a potential E2F5/UBE2T axis in gastric cancer, opening new avenues for the diagnosis and treatment of this malignancy." (PMID 39791716, 2024). "The team further targeted the upstream ubiquitin-binding enzyme UBE2T to develop a small molecular inhibitor M435-1279 with low cytotoxicity that can inhibit the progression of gastric cancer in vivo and in vitro." (PMID 37675097, 2023). "Previous study has shown that UBE2T was overexpressed in gastric cancer and predicted the poor prognosis." (PMID 34703898, 2021). "UBE2T silencing suppresses proliferation and induces cell cycle arrest and apoptosis in bladder cancer cells, and UBE2T knockdown inhibits gastric cancer progression." (PMID 33591950, 2021). "It is reported that UBE2T is closely related to the development and poor prognosis of several cancers such as prostate or gastric cancer." (PMID 30622320, 2019). "Together, these in vitro experiments suggest that suppression of UBE2T inhibits growth and colony formation and promotes apoptosis in gastric cancer cells." (PMID 28427240, 2017). "FCM results revealed that suppression of UBE2T increased G2/M cell cycle arrest and promoted apoptosis in gastric cancer cells." (PMID 28427240, 2017). "Next, we identified other factors and pathways that regulate or are regulated by UBE2T in gastric cancer using Affymetrix gene chip assays." (PMID 28427240, 2017). "Suppression of UBE2T also attenuated the invasive and metastatic abilities of gastric cancer cells by altering expression of epithelial-mesenchymal transition (EMT)-related factors." (PMID 28427240, 2017). "A xenograft model in which nude mice were injected with UBE2T knockdown human gastric cancer cells confirmed that suppression of UBE2T also decreased tumor formation and growth in vivo." (PMID 28427240, 2017). "The percentage of apoptotic cells greatly increased after the siRNA lentivirus infection in both SGC-7901 and BGC-823 cells (P < 0.01), indicating that suppression of UBE2T promoted both cell cycle arrest and apoptosis in gastric cancer cells." (PMID 28427240, 2017). "In both SGC-7901 and BGC-823 cells, the number of colonies was much lower on the 13th day after plating in shUBE2T groups compared to the shCtrl groups (P < 0.01), indicating that suppression of UBE2T inhibits colony formation in gastric cancer cells." (PMID 28427240, 2017).
gastric cancer (continued). "To confirm that these results were applicable in vivo, we used cancer cell xenotransplantation in nude female mice to examine the effects of UBE2T knockdown on gastric cancer progression." (PMID 28427240, 2017). "In this study, we comprehensively examined the roles, mechanisms, and regulation of UBE2T in gastric cancer for the first time." (PMID 28427240, 2017). "Together, all of these factors contribute to the UBE2T knockdown-induced inhibition of progression in gastric cancer both in vitro and in vivo." (PMID 28427240, 2017). "siRNA-mediated suppression of UBE2T inhibited gastric cancer cell proliferation and colony formation by promoting cell cycle arrest at G2/M phase and increasing apoptosis." (PMID 28427240, 2017). "We injected siRNA lentivirus-infected BGC-823 gastric cancer cells in which UBE2T expression was greatly inhibited into nude mice to generate the KD group." (PMID 28427240, 2017). "Because AGS and SGC-7901 cells have shown elevated invasive and metastatic activity in previous studies, we examined these cells to determine the effects of UBE2T on invasive and metastatic ability in gastric cancer cells." (PMID 28427240, 2017). "To further investigate the effects of UBE2T on gastric cancer progression, we also analyzed UBE2T expression in the tumor samples in TCGA database." (PMID 28427240, 2017). "High UBE2T expression in gastric cancer tissue microarrays correlates with poor prognosis and was proposed as a potential prognostic marker in gastric cancer progression." (PMID 27729585, 2016). "Upregulation of UBE2T levels has been disclosed to enhance gastric cancer development through RACK1 ubiquitination, and a novel powerful UBE2T inhibitor has been identified to suppress gastric cancer progression by blocking RACK1 ubiquitination after aberrant Wnt/β-catenin signaling." (PMID 36910645, 2023). "It was also found that silencing of UBE2T in bladder or gastric cancer could induce cell cycle arrest in the G2/M phase, thus promoting cell apoptosis and inhibiting tumour growth." (PMID 36088429, 2022). "In addition, a number of studies have confirmed that UBE2T plays a carcinogenic role in a variety of cancers, including lung cancer, gastric cancer, renal cell carcinoma, osteosarcoma, prostate cancer and glioma." (PMID 36088429, 2022). "On the one hand, UBE2T could promote gastric cancer cell progression via hyperactivating the Wnt/β-catenin pathway through the ubiquitination and degradation of RACK1." (PMID 34838005, 2021). "The downregulation of UBE2T could inhibit the progression of gastric cancer and performed the same function in prostate cancer." (PMID 31182966, 2019). "UBE2T knock-down increased E-Cadherin and β-Catenin expression and decreased Fibronectin and Vimentin expression, and these changes in expression likely inhibited metastasis and invasion in gastric cancer cells." (PMID 28427240, 2017). "Taken together, these results and previous research indicates that UBE2T might play a critical role in gastric cancer and might serve as useful potential biomarker and therapeutic target in gastric cancer patients." (PMID 28427240, 2017). "UBE2T was highly expressed in gastric tumors and gastric cancer cells." (PMID 28427240, 2017). "Here, we examined the effects of UBE2T on the progression of gastric cancer." (PMID 28427240, 2017). "UBE2T expression was then measured in different gastric cancer cell types using real-time PCR." (PMID 28427240, 2017). "UBE2T was widely expressed in all of the common human gastric carcinoma cells." (PMID 28427240, 2017). "Ectopic expression of UBE2T in gastric cancer cells promotes cell proliferation and induces epithelial–mesenchymal transition (EMT) by inhibiting the cell-to-cell adhesion factor E-cadherin, but elevating EMT-related factors N-cadherin, P-cadherin, and vimentin levels." (PMID 27729585, 2016).